RN7SL503P (RNA, 7SL, cytoplasmic 503, pseudogene)
Gene: Miscellaneous RNA gene on chromosome 1 (35,292,196 to 35,292,498, reverse strand). Ensembl gene ENSG00000240374.
Homologues: Orthologues: chimpanzee Metazoa_SRP (98% identical), macaque Metazoa_SRP (88% identical). Paralogues in human: RN7SL1 (82% identical), RN7SL2 (82% identical), RN7SL3 (81% identical), RN7SL126P (80% identical), RN7SL597P (79% identical), RN7SL650P (79% identical), RN7SL88P (79% identical), RN7SL147P (78% identical), RN7SL220P (78% identical), RN7SL508P (78% identical), RN7SL321P (78% identical), RN7SL45P (78% identical), and 701 more.